SCNN1D (sodium channel epithelial 1 subunit delta)
Description:
Potential alternative pore-forming subunit of the epithelial sodium channel (ENaC), capable of replacing the alpha/SCNN1A subunit, creating a more active channel with distinct properties. ENaC functions in epithelial tissues, where it facilitates the electrodiffusion of sodium ions from the extracellular fluid through the apical membrane of cells, with water following osmotically, regulating sodium balance and fluid homeostasis. This subunit could also function independently as a sodium channel or assemble into other tissue-specific heterotrimeric sodium channels. [Isoform 2]: ENaC channels including this isoform exhibit greater conductance.
Synonyms: ENaCD; DNACH; ENaCdelta; SCNED
Tractability: Small molecule: it belongs to a druggable protein family. Antibody: UniProt places it where antibodies can reach, with high confidence; its Gene Ontology location is reachable by antibodies, with high confidence; UniProt predicts a signal peptide or a membrane-spanning region; the Human Protein Atlas places it where antibodies can reach.
Gene: Protein-coding gene on chromosome 1 (1,280,436 to 1,292,029, forward strand). Ensembl gene ENSG00000162572.
Subcellular location: Apical cell membrane
Subcellular location (Human Protein Atlas): Actin filaments; Plasma membrane
Pathways (Reactome):
Sensory Perception: Sensory perception of salty taste
Transport of small molecules: Stimuli-sensing channels
Gene Ontology:
Molecular function: protein binding; sodium channel activity; ligand-gated sodium channel activity
Biological process: cellular response to acidic pH; intracellular sodium ion homeostasis; sodium ion import across plasma membrane; cellular response to aldosterone; cellular response to vasopressin; regulation of blood pressure; sensory perception of salty taste; sensory perception of sour taste; sodium ion transmembrane transport; sodium ion transport
Cellular component: actin cytoskeleton; apical plasma membrane; membrane; plasma membrane; sodium channel complex
Genetic constraint (gnomAD): Loss-of-function variants: 92 observed, 73.75 expected, observed/expected ratio (o/e) 1.25, 90% interval 1.05 to 1.48. The synonymous counts are far from expectation, so gnomAD's model fits this gene poorly and the ratio says little. Missense variants: 1,260 observed, 987.81 expected, observed/expected ratio (o/e) 1.28, 90% interval 1.22 to 1.34. Synonymous variants: 595 observed, 442.91 expected, observed/expected ratio (o/e) 1.34, 90% interval 1.25 to 1.44.
Homologues: Orthologues: chimpanzee SCNN1D (98% identical), macaque SCNN1D (69% identical), dog SCNN1D (49% identical), guinea pig Scnn1d (47% identical), tropical clawed frog scnn1d (28% identical), Caenorhabditis elegans mec-4 (14% identical), Caenorhabditis elegans mec-10 (14% identical), Caenorhabditis elegans acd-1 (13% identical), Caenorhabditis elegans delm-1 (13% identical), Caenorhabditis elegans acd-2 (13% identical), Caenorhabditis elegans acd-4 (12% identical), Caenorhabditis elegans delm-2 (12% identical), and 17 more. Paralogues in human: SCNN1A (29% identical), SCNN1G (21% identical), SCNN1B (20% identical), ASIC4 (15% identical), ASIC2 (14% identical), ASIC1 (14% identical), ASIC3 (14% identical), ASIC5 (13% identical).
Diseases named in the same sentence as SCNN1D in open-access papers:
SCNN1D is named in the same sentence as 8 diseases in open-access papers, as found by Europe PMC text mining. Sharing a sentence is not in itself a finding about the gene and the disease. The quoted sentences say what the papers report.
Liddle syndrome (2 papers, 2018 to 2024). A rare genetic form of low-renin hypertension characterized by hypertension associated with decreased plasma levels of potassium and aldosterone. "Variants in SCNN1D have been associated with various other pathological conditions, including hypertension and Liddle syndrome." (PMID 39554687, 2024). "Furthermore, some genes may be completely lacking in the zebrafish, such as the ENaC (epithelial Na channel) subunits (SCNN1A, SCNN1B, SCNN1G, and SCNN1D), mutations in which cause Liddle syndrome and pseudohypoaldosteronism type 1 in humans." (PMID 30200518, 2018).
influenza (1 paper, 2021). An acute viral infection of the respiratory tract, occurring in isolated cases, in epidemics, or in pandemics; it is caused by serologically different strains of viruses (influenzaviruses) designated A, B, and C, has a 3-day incubation period, and usually lasts for 3 to 10 days. "We have previously shown that RNAi silencing of the SCNN1D reduces influenza replication." (PMID 34714852, 2021). "The sodium channel gene SCNN1D was previously shown to be a pro-influenza host gene." (PMID 34714852, 2021).
infection (1 paper, 2024). The state of being infected such as from the introduction of a foreign agent such as serum, vaccine, antigenic substance or organism. "At the earlier time points post-infection, we did not observe any overlap with down-regulated mRNAs; however, 27 up-regulated mRNAs were common to all early treatment groups, including TLR3, IFIT5, IFIH1 (MDA5), MX1, RSAD2 (viperin), CMPK2, SOCS1, and SCNN1D." (PMID 38675946, 2024).
SCNN1D also shares sentences with these, for which no sentence is quoted: Hypertension (1 paper); neuroblastoma (1); pancreatic cancer (1); pseudohypoaldosteronism type 1 (1); pulmonary disease (1).